NAA38 (N-alpha-acetyltransferase 38, NatC auxiliary subunit)
Description:
Auxillary component of the N-terminal acetyltransferase C (NatC) complex which catalyzes acetylation of N-terminal methionine residues. N-terminal acetylation protects proteins from ubiquitination and degradation by the N-end rule pathway.
Synonyms: LSMD1; MAK31; PFAAP2; MGC14151
Tractability: Small molecule: a structure with a bound ligand is known. PROTAC: ubiquitination databases record sites on it; its protein half-life has been measured.
Gene: Protein-coding gene on chromosome 17 (7,856,685 to 7,885,238, reverse strand). Ensembl gene ENSG00000183011.
Subcellular location: Cytoplasm; Nucleus
Subcellular location (Human Protein Atlas): Nucleoplasm
Pathways (Reactome):
Vesicle-mediated transport: Retrograde transport at the Trans-Golgi-Network
Gene Ontology:
Molecular function: protein binding; RNA binding
Biological process: negative regulation of apoptotic process
Cellular component: cytoplasm; NatC complex; nucleoplasm; nucleus
Genetic constraint (gnomAD): Loss-of-function variants: 15 observed, 12.98 expected, observed/expected ratio (o/e) 1.16, 90% interval 0.77 to 1.73. The upper end of that interval is the gene's LOEUF score, 1.73, which puts it in group 6 of 6, group 1 being the genes least tolerant of losing a copy. Missense variants: 183 observed, 180.86 expected, observed/expected ratio (o/e) 1.01, 90% interval 0.9 to 1.14. Synonymous variants: 88 observed, 73.43 expected, observed/expected ratio (o/e) 1.2, 90% interval 1.01 to 1.43.
Homologues: Orthologues: chimpanzee NAA38 (98% identical), rabbit NAA38 (98% identical), dog NAA38 (97% identical), guinea pig NAA38 (96% identical), mouse Naa38 (95% identical), rat Naa38 (90% identical), macaque NAA38 (80% identical), tropical clawed frog naa38 (56% identical), zebrafish naa38 (56% identical), Drosophila melanogaster Sbat (30% identical), Caenorhabditis elegans natc-3 (22% identical).
Diseases named in the same sentence as NAA38 in open-access papers:
NAA38 is named in the same sentence as 4 diseases in open-access papers, as found by Europe PMC text mining. Sharing a sentence is not in itself a finding about the gene and the disease. The quoted sentences say what the papers report.
leukemia (1 paper, 2019). A malignant (clonal) hematologic disorder, involving hematopoietic stem cells and characterized by the presence of primitive or atypical myeloid or lymphoid cells in the bone marrow and the blood. "To further explore the clinical significance of these hub genes (SUGP1, DHX16, FUS, HNRNPR, DHX15, NAA38, SKIV2L2, and PLRG1), we used a series of online tools to evaluate the clinical expression of these hub genes in leukemia." (PMID 31766457, 2019).
cancer (2 papers, 2020 to 2023). A tumor composed of atypical neoplastic, often pleomorphic cells that invade other tissues. "Within the DepMap genome-wide CRISPR knockout (KO) screen consisting of 739 cell lines of diverse tissue origin, most NATs were essential to all or to a subset of cancer cells, with the exception of NAA60, NAA80, NAA38, NAA11 and NAA16." (PMID 32942614, 2020). "NAA38 has not yet been investigated for its specific role in cancer development, but as part of the NatC complex, it inhibits the apoptotic process and is also a potential target." (PMID 37415732, 2023).
NAA38 also shares sentences with these, for which no sentence is quoted: tumor (2 papers); endometrial cancer (1).